CTCF (CCCTC-binding factor)
Diseases named in the same sentence as CTCF in open-access papers (continued):
Sharing a sentence is not in itself a finding about the gene and the disease.
invasive breast carcinoma (6 papers, 2004 to 2024). A carcinoma that infiltrates the breast parenchyma. "Another example is the loss of Nm23-H1 in invasive breast cancer caused by the downregulation of CTCF and EGR1." (PMID 36120336, 2022). "In the present study, tissue microarray technology was used to study the expression pattern of CTCF immunohistochemically in 344 cases of invasive breast carcinoma and its expression was correlated with clinicopathological variables and patient outcome." (PMID 15354217, 2004). "A low level of Egr-1 and CTCF is usually observed in invasive breast cancer." (PMID 37046823, 2023). "Thus, in the present study, protein expression of CTCF was examined immunohistochemically in a large series to assess its possible role in invasive breast cancer." (PMID 15354217, 2004).
myeloid leukemia (6 papers, 2015 to 2024). A clonal proliferation of myeloid cells and their precursors in the bone marrow, peripheral blood, and spleen. "Myeloid leukemia associated with DS (ML-DS) is preceded by a preleukemic phase called transient abnormal myelopoiesis driven by GATA1 gene mutations and progresses to ML-DS via additional mutations in cohesin genes, CTCF, RAS, or JAK/STAT pathway genes." (PMID 37895004, 2023).
osteosarcoma (6 papers, 2021 to 2025). A usually aggressive malignant bone-forming mesenchymal neoplasm, predominantly affecting adolescents and young adults. "Herein, we aim to investigate the role of cisplatin- (CDDP-) resistant osteosarcoma- (OS-) derived exosomal CTCF in OS cell resistance to CDDP and its mechanistic basis." (PMID 35693981, 2022). "We then applied the same treatment to the osteosarcoma cell line and expected to observe a higher impact due to the CTCF depletion." (PMID 35409255, 2022).
Alzheimer disease (5 papers, 2021 to 2026). A progressive, neurodegenerative disease characterized by loss of function and death of nerve cells in several areas of the brain leading to loss of cognitive function such as memory and language. "Of note, 29 out of 44 genes showed an interaction with the CTCF protein, a transcription factor that has been associated with Alzheimer’s disease and synaptic organization (adjusted p value = 0.0011) 21,22." (PMID 38182665, 2024). "Non-coding Alzheimer’s disease risk variants can influence gene expression by affecting miRNA binding and those located within enhancers and within CTCF sites may influence gene expression through alterations in chromatin states." (PMID 33959712, 2021). "Similarly, although CTCF mutations and reduced CTCF binding have been implicated in neurodevelopmental disorders wherein neurons acquire high levels of DSBs, such as Alzheimer’s disease, their impact on the DDR has not been investigated." (PMID 41338928, 2026).
Cognitive impairment (5 papers, 2021 to 2025). Abnormal cognition is characterized by deficits in thinking, reasoning, or remembering. "Previous studies demonstrated that neurodegenerative diseases are associated with some TFs, among which CTCF is closely related to cognitive disorders." (PMID 36360189, 2022). "These downregulated pathways elucidate the phenotypes of small size, stem cell depletion, and abnormal neurodevelopment in the mutant organoids, consistent with the clinical manifestations of growth retardation and intellectual impairment in heterozygous CTCF mutant cases." (PMID 38951485, 2024). "These cognitive impairments are likely due to the loss of glutamatergic neurons in the cortex, particularly in the ACC, as inhibitory neurons in the striatum are relatively intact in adult CTCF cKO mice." (PMID 33402211, 2021).
diabetes (5 papers, 2014 to 2023). "PRKCZ hypermethylation plays a vital role in several diseases, such as type 2 diabetes mellitus, CTCF deletion syndrome, and postmenopausal osteoporosis." (PMID 36077689, 2022). "CTCF is a general TF that has been reported to mediate the effects of insulin on glucagon expression and therefore is a possible new target for diabetes treatment." (PMID 25399255, 2014). "We observed that CTCF and Pol2B were enriched at sites of reduced methylation in the peripheral blood derived from T1D individuals with DN, whereas DNA methylation was more abundant at the same gene sequences in individuals with diabetes with improved or normal renal function." (PMID 36633903, 2023). "Likewise, the genomic region within UPF1 gene, covering the top-ranked CpG site is associated with CTCF, Egr1, and two more transcription factors: MYC—involved in the pathogenesis of diabetes, and PU1—initiating insulin resistance as well as regulating lipolysis." (PMID 30545422, 2018).
Sepsis (5 papers, 2018 to 2023). Sepsis is defined as life-threatening organ dysfunction caused by a dysregulated host response to infection. "At the time of diagnosis, sepsis following abdominal surgery was associated with increased CTCF occupancy at intergenic sites adjacent to classical HLA genes, accompanied by reduced transcription of HLA-DRA, HLA-DRB1, HLA-DPA1 and HLA-DPB1." (PMID 37878653, 2023). "Since the observed sepsis-associated increase of CTCF occupancy exclusively occurred at binding sites adjacent to classical HLA class II isotypes (HLA-DR, HLA-DQ and HLA-DP), transcription of the corresponding genes was analysed." (PMID 33939725, 2021). "Specifically, sepsis was associated with a selective increase of CTCF enrichment at three binding sites corresponding to C1, XL9, and C2, whereas no differential CTCF occupancy was detected at the other binding sites across the locus." (PMID 35052743, 2021). "For the first time, our study reveals reduced expression of MHC-II- and CIITA genes associated with specific changes in binding of CTCF in the intergenic region in critically ill patients suffering from sepsis." (PMID 30212590, 2018). "Sepsis was associated with an increased CTCF expression (**p<0.01, control vs sepsis T1)." (PMID 33939725, 2021). "Recently, we could demonstrate in circulating monocytes of patients with sepsis, that an increased CTCF-occupancy at this intergenic region is associated with selective changes in adjacent HLA-gene expression." (PMID 33939725, 2021). "Compared to a matched control cohort, we could demonstrate that postoperative sepsis was associated with a selective and persistent increase in CTCF enrichment at binding sites located next to classical HLA genes that code for proteins expressed on the surface of antigen-presenting cells." (PMID 33939725, 2021). "Thus, although we cannot exclude that sepsis-associated stimuli persist and constantly induce CTCF-occupancy in peripheral blood monocytes, there is certain probability that sepsis might lead to endurable epigenetic changes." (PMID 33939725, 2021). "Siegler and the group designed an experiment to study sepsis-induced CCCTC-Binding Factor (CTCF) differential occupancy in post-operative sepsis patients and its contribution to altering the transcriptional response of human monocytes during illness." (PMID 35831411, 2022). "Using chromatin from isolated CD14++ monocytes, ChIP experiments and subsequent qPCR revealed a differential CTCF occupancy at the investigated sites during postoperative sepsis." (PMID 33939725, 2021). "As an important finding, these interactions were confirmed for pairs of CTCF-sites and promoter regions of genes, which also displayed sepsis-induced alterations in our study (CM1 and HLA-DRA, CM2 and HLA-DRB1, CM9 and HLA-DPA1 and CM9 and HLA-DB1)." (PMID 33939725, 2021). "Taken together, these findings indicate an involvement of CTCF in modulating the transcriptional response of functionally impaired monocytes during the initial phase of postoperative human sepsis." (PMID 33939725, 2021). "Both genes neighbour CTCF binding sites with an observed increase in CTCF occupancy during postoperative sepsis (CM1 and CM2)." (PMID 33939725, 2021). "Our findings indicate a sepsis-induced enhancer blockade mediated by variation of CTCF at the intergenic sequence XL9 as a potential mechanism contributing to an immunosuppressive phenotype in this critically ill patient population." (PMID 30212590, 2018). "Overall, our findings indicate a sepsis-induced enhancer blockade mediated by variation of CTCF at the intergenic sequence XL9 in altered monocytes during immunosuppression." (PMID 30212590, 2018). "In our view, this points towards other mechanisms that might control CTCF occupancy at XL9 during immune suppressive sepsis or inhibit further CTCF binding during a healthy state." (PMID 30212590, 2018).
Sepsis (continued). "Together with the present findings as well as own previous observations in patients with sepsis, this supports the hypothesis of a complex regulatory model, where CTCF may regulate gene expression by modulating the topological architecture of the entire MHC-II region." (PMID 37878653, 2023). "This is also in line with a previously conducted study of our group and supports the assumption that the proposed interaction between CIITA, CTCF and its binding sites might be disturbed during critical illness like sepsis, resulting in a decoupled co-regulation of HLA genes." (PMID 33939725, 2021). "Hence, we speculate a significant change of the proposed interaction and a potential predominance of the insulator function of CTCF during sepsis." (PMID 30212590, 2018). "Since XL9 was identified as a CTCF-binding site and may thus function as potential enhancer-blocking sequence, our findings support the hypothesis that this region represents a relevant regulatory element of the MHC-II locus modulated by CTCF in immune-compromised patients suffering from sepsis." (PMID 30212590, 2018). "Moreover, an inverse correlation of CTCF and CIITA expression was detected in patients with postoperative sepsis (R2 = 0.48; p<0.05)." (PMID 33939725, 2021). "Additional experiments revealed that the observed elevation in CTCF expression, CTCF binding at CM1, CM2, CM3 and CM9 as well as the reduced expression of adjacent classical HLA genes HLA-DRA, HLA-DRB1, HLA-DPA1 and HLA-DPB1 persisted in all patients with postoperative sepsis." (PMID 33939725, 2021). "CTCF has been recognised as an important genome-wide regulator of gene expression in a variety of cell types including phagocytes; however, its specific impact on antigen-presentation in sepsis-induced immune suppression has not been investigated so far." (PMID 30212590, 2018). "The impact of CTCF on global gene expression has been investigated in numerous cell types including those of the innate immune system; however, its role in the transcriptional regulation of antigen presentation during postoperative human sepsis has not been elucidated so far." (PMID 33939725, 2021). "Neither monocytic HLA-DR surface expression, nor CTCF gene expression and its binding within the MHC-II region or HLA class II gene expression differed between sepsis survivors and non-survivors." (PMID 33939725, 2021).
autoimmune disease (4 papers, 2013 to 2025). A disorder resulting from loss of function or tissue destruction of an organ or multiple organs, arising from humoral or cellular immune responses of the individual to their own tissue constituents. "We tested for enrichment of GWAS variants in CTCF peaks using fGWAS, for a number of autoimmune diseases where T cells play an important role and for which summary statistics were available (PsA, RA, JIA)." (PMID 39930543, 2025). "In recent years, many studies have found that CTCF may be closely related to autoimmune diseases." (PMID 33133081, 2020). "We found that 90.1% of target genes are regulated by distal SNPs involving several TFs (e.g., the DNA-binding protein CCCTC-binding factor [CTCF]), suggesting the importance of long-range chromatin interaction in autoimmune diseases." (PMID 32879140, 2020).
developmental delay (4 papers, 2019 to 2024). "Most of these variants reported in the study were de novo mutations, except for two types of familial CTCF mutations with mild effects of developmental delay." (PMID 35993175, 2022). "CTCF dosage deficiencies has been linked to developmental delay and intellectual disability." (PMID 37841836, 2023). "Patients with a heterozygous, four base pair deletion in the 5' end of the coding sequence of CTCF display developmental delay, intellectual disability and microcephaly (MIM#615502)." (PMID 35993175, 2022). "We further note that the pattern for deletions from those of developmental delay patients differs from the pattern seen for cancer deletions, which actually display enrichment for breakpoints at highly expressed TSSs and CTCF clusters." (PMID 30659153, 2019).
endometriosis (4 papers, 2022 to 2025). The growth of functional endometrial tissue in anatomic sites outside the uterine body. "Despite previous associations of CTCF with endometriosis, its implication in endometrial progression and function has not been directly proposed until now." (PMID 37700285, 2023). "The role of “hubs” in these endometriosis-significant interactions was performed by proteins such as MYC (participates in 7 pair interactions), POU3F2 (6 pair interactions) and CTCF (4 pair interactions)." (PMID 41373783, 2025). "The results indicated that 13 TFs were identified in both SLE and endometriosis, and 6 of them (EP300, TCF12, CTCF, POLR2A, CEBPB and NFIC) can act on four potential co-diagnostic genes simultaneously." (PMID 39744159, 2025).
esophageal cancer (4 papers, 2016 to 2023). A primary or metastatic malignant neoplasm involving the esophagus. "Its motifs were mostly mutated in digestive tract tumors (3,784 CTCF mutated motifs, P-value = 0.0097), esophagus cancers (1,154, P-value = 0.0097), liver-HCC (1,570, P-value = 0.0097), and skin melanomas (1, 016, P-value = 0.0097)." (PMID 34282050, 2021). "CTCF, MLLT1, and TGIF2 are transcriptional regulators that play crucial roles in the transcription of important proto-oncogenes such as FOXM1, MYC, HoxA gene family, and OCT4 in multiple cancer types including HCC, esophageal cancer, and lung adenocarcinoma." (PMID 37335919, 2023).
Friedreich ataxia (4 papers, 2009 to 2014). An inherited condition that affects the nervous system and causes movement problems. "A substantial increase in H3K27me3 was shown in Friedreich ataxia patients, who have a severe depletion of CTCF in the 5′ untranslated sequence of the frataxin gene (FXN)." (PMID 25294833, 2014). "In Friedreich ataxia (FRDA), caused by expansion of a GAA repeat sequence in intron 1 of the FXN gene, CTCF depletion was observed in the 5′ UTR of the mutant alleles." (PMID 23874213, 2013).
glioblastoma (4 papers, 2016 to 2023). The most malignant astrocytic tumor (WHO grade IV). "Therefore, in glioblastoma cells and in regulatory regions as for the miR-181c, CTCF disruption can be caused by specific mutations that affect its binding to DNA." (PMID 26983574, 2016). "We infected the glioblastoma U87MG cell line with a lentivirus expressing a doxycycline inducible shRNAi against human CTCF." (PMID 26983574, 2016). "We confirmed binding of CTCF to the promoter region of miR-181c in the glioblastoma cell line U87MG and K562 cells." (PMID 26983574, 2016). "To explore the epigenetic regulation of the miR-181c we evaluated its expression using RT-qPCR and the in vivo binding of the CCCTC-binding factor (CTCF) to its regulatory region in different glioblastoma cell lines." (PMID 26983574, 2016). "This is supported by the depletion of CTCF in glioblastoma cells affecting the expression levels of NOTCH2 as a target of miR-181c." (PMID 26983574, 2016). "In the present study we observed that CTCF knockdown induces overexpression of NOTCH2 gene in U87MG glioblastoma cells possibly as a consequence of the epigenetic silencing by DNA methylation of miR-181c." (PMID 26983574, 2016). "Here we explored the epigenetic regulatory processes responsible for the deregulation of miR-181c in glioblastoma cells; in particular, we asked whether the nuclear factor CTCF participates in its epigenetic regulation." (PMID 26983574, 2016). "Since CTCF binds to a CpG rich region in the promoter of miR-181c we hypothesized that DNA methylation and CTCF could be critical regulators of miR-181c expression in glioblastoma." (PMID 26983574, 2016). "Therefore CTCF loss causes the epigenetic silencing of miR-181c by DNA methylation and the inability of the miR-181c to diminish the levels of NOTCH2 transcripts in glioblastoma U87MG cells." (PMID 26983574, 2016). "In contrast, CTCF does not bind the promoter region of the aggressive glioblastoma cell line T98G." (PMID 26983574, 2016). "However, if CTCF interacts with the miR-181c promoter in the glioblastoma cell lines used in this study is not known." (PMID 26983574, 2016).
lung adenocarcinoma (4 papers, 2023 to 2024). A carcinoma that arises from the lung and is characterized by the presence of malignant glandular epithelial cells. "We observed that PRSS1 and CTCF mutations in lung adenocarcinomas and skin melanomas show similar resistance-conferring effects to KRAS and NRAS mutations when treated with EGFR and BRAF inhibitors." (PMID 39160568, 2024). "Histone modifications, CTCF, and RNA polymerase II binding to NAGS, CPS1, and citrin regulatory regions in the liver, lung, and A549 lung adenocarcinoma cells suggest that all three genes appear to be poised for expression in the lung tissue." (PMID 37047726, 2023).
metastatic disease (4 papers, 2016 to 2022). "The enrichment for CTCF mutations that we see in metastatic disease is not an anticipated resistance mechanism." (PMID 32374727, 2020).
T-cell acute lymphoblastic leukemia (4 papers, 2016 to 2021). Acute lymphoblastic leukemia of T-cell origin. "Consistent with our results a recent study showed that the disruption of chromatin boundary sites may activate proto-oncogenes in T-cell acute lymphoblastic leukemia, and observed a similar excess of mutations at CTCF sites." (PMID 27490693, 2016). "An example of this occurs in T-cell acute lymphoblastic leukemia (T-ALL) where a mutation in a CTCF anchor motif disrupts the insulated neighborhood where the T-ALL-associated oncogene, TAL BHLH transcription factor 1 (TAL1), resides." (PMID 30268153, 2018).
triple-negative breast carcinoma (4 papers, 2018 to 2022). An invasive breast carcinoma which is negative for expression of estrogen receptor (ER), progesterone receptor (PR), and human epidermal growth factor receptor 2 (HER2). "The low levels of CTCF in our cell lines tightly mimic those observed in vivo from a panel of tumor xenografts derived from a distinct set of triple-negative breast cancer patient tumors." (PMID 36037342, 2022). "Having the possibility of directing insertion of genetic cargo into desired loci, others used the knock-in potential of CRISPR/Cas9 to safely transfer a tumor suppressor gene, the CCCTC-binding factor (CTCF) into the AAVS1 integration locus of triple-negative breast cancer cells MDA-MB-231." (PMID 36139356, 2022). "We find that the chromatin insulating protein machinery, including CTCF, is suppressed and re-expressed, coincident with broad alterations in chromatin accessibility, during EMT/MET, and is lower in triple-negative breast cancer cell lines with EMT features." (PMID 35008373, 2022). "Among REST, CTCF, and CEBPB, CEBPB is the only member that was significantly enriched in C19MChigh group (REST and CTCF data were not shown) and hence we investigated whether CEBPB is functional in triple negative breast cancers." (PMID 30335837, 2018).
B cell lymphoma (3 papers, 2014 to 2020). "In B cell lymphomas, increased expression of CTCF is associated with down-regulation of c-myc, resulting in cell growth arrest and apoptosis." (PMID 24393203, 2014). "In order to experimentally test the hypothesis that cohesin occupancy at a given site is CTCF-dependent, we used a mouse CH12 B cell lymphoma cell line in which endogenous CTCF has been homozygously mutated." (PMID 31937660, 2020).